MECOM (MDS1 and EVI1 complex locus)
Diseases named in the same sentence as MECOM in open-access papers (continued):
Sharing a sentence is not in itself a finding about the gene and the disease.
ovarian carcinoma (continued). "Thus, epigenetic targeting with E-JIB04 and modulating MECOM expression could have significant clinical implications for ovarian cancers." (PMID 40664642, 2025). "In totality, our results thus present a new epigenetic based therapeutic opportunity to target ovarian cancer cells harboring MECOM amplification and may also suggest potential of combining JIB-04 epidrug as neo-adjuvant with standard platin based chemotherapy." (PMID 40664642, 2025). "Moreover, MECOM has emerged as a promising therapeutic target in epithelial ovarian cancer." (PMID 41154754, 2025). "In ovarian cancer, EVI1/MECOM drives disease progression by interacting with various genes such as PAX8, TGF-β, PBK, and also regulating estrogen signaling." (PMID 40664642, 2025). "The therapeutic efficacy of JIB-04 was further demonstrated in mice bearing ovarian cancer cell xenografts, where JIB-04 slowed down the tumor growth in corroboration with diminishing MECOM expression." (PMID 40664642, 2025). "To unravel oncogenic function of MECOM, we selected OVSAHO and SKOV3 as ovarian cancer cell lines harboring high MECOM copy number amplification, and A2780 was selected as cell line lacking MECOM amplification." (PMID 40664642, 2025). "In summary, most preclinical studies support the role of MECOM and/or EVI1 overexpression in ovarian cancer tumorigenesis." (PMID 41340866, 2025). "Several genes have been confirmed to be closely related to the occurrence and progression of ovarian cancer, including SNAI2, VCAM1, BRCA1, MMP2, MECOM, MXS1, PARP1 and so on." (PMID 35090503, 2022). "For instance, MDS1 and EVI1 complex loci (MECOM) interact with PAX8 and drive oncogenic functions in ovarian cancer." (PMID 34722520, 2021). "The differential amplification in PIK3CA, MECOM, and ATR while interesting signals require validation using an orthogonal method and a larger cohort given the high degree of aneuploidy found in ovarian carcinoma." (PMID 33811746, 2021). "The highest of these, by a very narrow margin (–log q value 93.88 vs. 93.43), does not intersect with any genes, while the other peak overlaps with MECOM (MDS/EVI1); there is good evidence for this gene being an oncogene in ovarian cancer." (PMID 20844748, 2010). "Here, our results unveil a previously undescribed role for MECOM in the transcriptional regulation of KRAS oncogene at chromatin level, consolidating its importance as a relevant target for therapeutic intervention in ovarian cancer." (PMID 40664642, 2025). "As JIB-04 treatment reduced MECOM expression in ovarian cells harboring MECOM amplification, we aimed to explore the tumor inhibitory activity of JIB-04 towards ovarian cancer cells harboring MECOM amplification, and efficacy studies were performed in SKOV3 cell-derived ovarian tumor mice model." (PMID 40664642, 2025). "To inquire for a potential epigenetic regulation of MECOM by histone methylation, we performed chromatin immunoprecipitation of ovarian cancer cells treated with or without E-JIB-04 inhibitor using ChIP-grade histone H3K4me3, H3K9me3, and H3K27me3 antibodies." (PMID 40664642, 2025). "Despite these insights, the precise mechanisms by which MECOM regulates proliferation and migration in ovarian cancer remain underexplored, and no specific inhibitors or targeted therapies for MECOM are currently available." (PMID 40664642, 2025). "Collectively, our findings highlight MECOM as a therapeutically actionable oncogene in ovarian cancer and demonstrate that small-molecule inhibitors like JIB-04, by epigenetically targeting amplified oncogenes, offer a promising strategy for ovarian cancer treatment." (PMID 40664642, 2025). "However, in ovarian cancer cell lines, treatment with CDK7 inhibitor (THZ1) resulted in decreased expression of MECOM and decreased cell survival with no off-target effect in benign fallopian tube cell lines." (PMID 41340866, 2025).
myeloid malignancies (12 papers, 2015 to 2025). "A comprehensive review of partner genomic loci and genes mutated in myeloid neoplasms with MECOM rearrangement was also conducted." (PMID 40255434, 2025). "Two patients had LV insertion at the MECOM locus, a known susceptibility locus for myeloid malignancies and an inhibitor of cell cycle progression and differentiation of HSCs." (PMID 39276676, 2024). "Elevated MECOM expression has been associated with myeloid neoplasms, particularly tMN and those with KMT2Ar, and is associated with a poor prognosis in both adult and pediatric myeloid neoplasms." (PMID 33579957, 2021). "Recent findings have suggested MECOM as a novel candidate gene for hereditary hematological malignancies; indeed, a novel germline mutation within the ninth zinc finger motif was reported in a family with developed myeloid malignancies." (PMID 32290321, 2020). "Further functional verification of AF4 involvement in MECOM rearrangement-based myeloid neoplasms will help elucidate the corresponding molecular etiology and identify therapeutic targets." (PMID 40255434, 2025). "Our study provides further insight into the molecular etiology of MECOM translocation-based myeloid neoplasms." (PMID 40255434, 2025). "To date, more than 30 genomic loci have been reported to fuse with the MECOM locus in human myeloid neoplasms." (PMID 40255434, 2025). "For other myeloid neoplasms, MECOM rearrangements are the most common additional aberrations detected by OGM." (PMID 40361363, 2025). "The AF4 gene and the transcription elongation control pathways are proposed as potential therapeutic targets for MECOM-rearranged myeloid neoplasms." (PMID 40255434, 2025). "Chromosomal translocations involving the MECOM locus at 3q26.2 account for less than 1% of myeloid neoplasms." (PMID 40255434, 2025). "Chromosomal rearrangements, mutations and/or the aberrant expressions of PRDM2, PRDM3/MECOM and PRDM16 were reported in lymphoid/myeloid malignancies in accordance with their roles in the hematopoietic stem cell differentiation and homeostasis control." (PMID 34769459, 2021). "Myeloid neoplasms involving MECOM rearrangements can be classified into two groups." (PMID 40255434, 2025). "The reduction or removal of blast percentage thresholds in recent AML classifications, including the ICC and WHO frameworks, reflects the recognition that MECOM-rearranged myeloid neoplasms exhibit aggressive biology and a high propensity for leukemic transformation, even at low blast counts." (PMID 41283235, 2025). "However, not all patients with MECOM locus integrations have developed therapy-related myeloid neoplasms (tMN), suggesting that there are likely additional oncogenic factors at play that have yet to be identified." (PMID 39276676, 2024).
breast cancer (9 papers, 2020 to 2025). A primary or metastatic malignant neoplasm involving the breast. "Upon inquiring for potential genes contributing to cisplatin resistance due to MECOM amplification, we identified transcription co-activator SUB1, a proposed carcinogenic gene implicated in hepatoblastoma malignancy and associated with poor prognosis in breast cancer metastasis." (PMID 40664642, 2025). "Although research on W6134 and XY018 in diverse breast cancers is growing, significant gaps remain in understanding their roles in canine mammary cancer cells and how they influence the key inflammatory gene expression such as CXCL10 and MECOM." (PMID 40805064, 2025). "MECOM and FLI1 activities were decreased, while breast cancer promoted FOSB and RFX2 activities." (PMID 37153595, 2023).
myelodysplastic syndrome (8 papers, 2010 to 2023). A clonal hematopoietic disorder characterized by dysplasia and ineffective hematopoiesis in one or more of the hematopoietic cell lines. "Recently, loss-of-function mutations in myelodysplastic syndrome (MDS) and ecotropic virus integration site-1 (EVI1) complex locus (MECOM) have been identified that lead to a severe neonatal bone marrow failure syndrome." (PMID 36522544, 2023).
colorectal cancer (7 papers, 2012 to 2025). A primary or metastatic malignant neoplasm that affects the colon or rectum. "Mutations resulting in aberrant expression of the MECOM have also been found in many types of solid cancers, including colorectal cancer, as well as in acute myeloid leukemia." (PMID 33432064, 2021). "In colorectal cancer, MECOM preferentially activates the proto-oncogene ETS2 by binding to its distal super-enhancer." (PMID 40664642, 2025). "It should be emphasized that MECOM, eEF1A2, and U1 risk alleles have shown detrimental effects in other inflammatory diseases including human IBD and colorectal cancer." (PMID 33432064, 2021). "To further check the role of PRKACB, MECOM, PLA2G4C, FGF2 and FGF in colorectal cancer, we further analyzed the genes involved in the MAPK pathway for their association with patient’s survival using the survExpress online tool." (PMID 28749961, 2017).
endometrial cancer (6 papers, 2021 to 2026). Primary or metastatic malignant neoplasm involving the endometrium (mucous membrane that lines the endometrial cavity). "We postulate that investigating vulnerabilities of MECOM amplified tumors will be a useful strategy to reduce mortality associated with CNH endometrial cancer." (PMID 41340866, 2025). "Furthermore, even in the absence of co-amplification of CCNE1 or ERBB2, MECOM amplification alone conferred a similar two-fold increase in risk, suggesting that MECOM amplification may independently identify an aggressive subset of endometrial cancers." (PMID 41340866, 2025). "When stratified by molecular subtype, race, stage and histology, MECOM amplification was most likely to occur in CNH endometrial cancer, tumors obtained from Black women, those diagnosed at advanced stages (III/IV) and in serous tumors." (PMID 41340866, 2025). "To determine the role of MECOM and/or EV1/MDS1 in endometrial cancer, we performed a broad literature review inclusive of the most common gynecologic cancers (endometrial/uterine and ovarian/fallopian tube)." (PMID 41340866, 2025). "In summary, the overexpression of MECOM in HEC-1-A uterine endometrial cancer cells promoted cell proliferation, cell cycle progression, and cell migration ability while inhibiting cell apoptosis." (PMID 39468462, 2024). "Through bioinformatics analysis, it was discovered that the expression of MECOM in UCEC (Uterine Corpus Endometrial Carcinoma) tissues is significantly higher than in normal tissues, suggesting its potential key role in tumor development and progression." (PMID 39468462, 2024). "•MECOM is the most frequently amplified gene in endometrial cancers (EC) of the TCGA." (PMID 41340866, 2025). "Here, we propose that MECOM amplified endometrial cancer is a novel subset of CNH tumors." (PMID 41340866, 2025). "We recognize that while preclinical studies have shown that MECOM amplified tumors are sensitive to transcriptional targeted inhibitors in high grade serous ovarian cancer, there is a paucity of data in preclinical models of endometrial cancer." (PMID 41340866, 2025). "Further studies are warranted to explore the role of MECOM and its isoforms in CNH endometrial cancer." (PMID 41340866, 2025). "Notably, MECOM amplification co-occurred with CCNE1 and ERBB2, two subsets of endometrial cancer known for their poor prognosis in CNH tumors." (PMID 41340866, 2025). "In this study, several uterine endometrial cancer cell lines (HEC-1-A, AN3 CA, HEC-1B, RL95-2, KLE) and a normal cervical epithelial cell line VK2/E6E7 were chosen to investigate the expression of MECOM." (PMID 39468462, 2024).
glioblastoma (5 papers, 2019 to 2025). The most malignant astrocytic tumor (WHO grade IV). "The gene MECOM, associated with poor prognosis in glioblastoma, has been demonstrated to interact with GATA2 and other transcription factors." (PMID 41154393, 2025). "MECOM was associated with the proliferation of glioblastoma multiforme cells." (PMID 30970615, 2019). "Because ISH staining for the prototypical endothelial marker CD31 (PECAM1) is not available in the Ivy GAP, analysis of glioblastoma vasculature considered ESM1, MECOM, and ENPEP; genes known to be enriched in endothelial cells." (PMID 39724753, 2024).
myeloid leukemia (5 papers, 2009 to 2025). A clonal proliferation of myeloid cells and their precursors in the bone marrow, peripheral blood, and spleen. "Eventually these patients developed myelodysplastic syndrome (MDS) with chromosome 7 monosomy, driven by transactivation and overexpression of MDS-EVI1 complex locus (MECOM), a well-known proto-oncogene involved in the genesis of myeloid leukaemia and chromosomal instability." (PMID 40200078, 2025). "PRDM3/MECOM (MDS1 and EVI1 Complex) locus was firstly identified as a site of proviral insertion in murine myeloid leukemias." (PMID 32290321, 2020).
myeloproliferative neoplasm (5 papers, 2015 to 2025). A clonal hematopoietic stem cell disorder, characterized by proliferation in the bone marrow of one or more of the myeloid (i.e., granulocytic, erythroid, megakaryocytic, and mast cell) lineages. "Germline variations at JAK2, TERT, HBS1L-MYB and MECOM have been found to associate with myeloproliferative neoplasms (MPNs) in European populations." (PMID 29100304, 2017). "MECOM-driven AML and AML transformed from myeloproliferative neoplasms (post-MPN AML) frequently exhibit aggressive clonal evolution, profound chemoresistance, and extensive remodeling of the bone marrow microenvironment." (PMID 41463143, 2025).
pancreatic cancer (5 papers, 2020 to 2021). "We identified MECOM, a transcription factor known to be involved in (pancreatic) cancer, as the most uniquely expressed gene in the dedifferentiated acinar cells." (PMID 33762742, 2021). "MECOM (also known as PRDM3) is a nuclear TF known to ablate inflammatory responses and tumorigenesis in pancreatic cancer contexts." (PMID 34367349, 2021). "In PC, MECOM was shown to be a critical regulator that suppresses acinar cell death by permitting cellular dedifferentiation, but there are limited studies regarding the other seven genes in pancreatic cancer." (PMID 34722520, 2021). "We hypothesized that MECOM plays a role during acinar cell dedifferentiation, an event that initiates pancreatic tumor development, and this in connection to SOX9 and ERK signaling." (PMID 33762742, 2021). "Previously, a role for MECOM in pancreas cancer was proposed." (PMID 33762742, 2021). "Although the MECOM transcription factor is a known oncogene with a role in apoptosis and pancreatic tumor formation, its function in acinar cell (de)differentiation was unknown." (PMID 33762742, 2021). "In addition, significant upregulation of a number of HMTs such as KMT5B, KMT2D (MLL2), NSD3 (nuclear SET domain-containing protein 3), PRDM16, MECOM (MDS1 and EVI1 complex locus protein) and NSD1 was observed in MCF7, MDA-MB-231, and pancreatic carcinoma PANC1 cell lines." (PMID 34884658, 2021).
serous ovarian cancer (5 papers, 2021 to 2025). "MECOM has recently been classified as a master transcription factor and an oncogene of interest in high grade serous ovarian cancer." (PMID 41340866, 2025). "In addition, by binning TCGA high-grade serous ovarian cancer (HGSOC) cases (n = 430) based on either PAX8 or PRDM3 expression quartiles, we observed that cases with high PAX8 and MECOM expression displayed significantly higher Signature Score compared to others." (PMID 33903593, 2021). "Successfully targeting MECOM and/or EVI1 expression with epigenetic drugs suggests a role for MECOM directed therapy in high grade serous ovarian cancer (Chen, 2024, Nameki, 2023)." (PMID 41340866, 2025). "The GSE18520 dataset compared gene expression of patients with high grade serous ovarian cancer (HGSOC) (n = 53) and matched controls (n = 10) and mean MECOM gene expression in these samples were analysed." (PMID 40664642, 2025). "The transcription factors MECOM, PAX8, SOX17 and WT1 are candidate master regulators of high-grade serous 'ovarian' cancer (HGSC), yet their cooperative role in the hypothesized tissue of origin, the fallopian tube secretory epithelium (FTSEC) is unknown." (PMID 37090516, 2023).
chronic myeloid leukemia (4 papers, 2013 to 2020). "MECOM (MDS1 and EV1 complex locus) encodes ecotropic viral integration site 1 (EVI1), an oncogenic zinc finger transcription factor known to be overexpressed in acute and chronic myeloid leukemia and to correlate with poor patient survival." (PMID 26221190, 2015). "In chronic myeloid leukemia (CML), expression of the oncogene MECOM correlates with progression." (PMID 27825300, 2016).
Thrombocytopenia (4 papers, 2023 to 2025). A reduction in the number of circulating thrombocytes. "Like other subtypes of AML, cases with MECOM rearrangements typically present with anemia, thrombocytopenia, and either leukopenia or leukocytosis." (PMID 41283235, 2025).
lung adenocarcinoma (3 papers, 2015 to 2022). A carcinoma that arises from the lung and is characterized by the presence of malignant glandular epithelial cells. "MDS1 and EVI1 complex locus (MECOM) serves as one of the crucial prognostic markers handling immune cell responses in lung adenocarcinoma." (PMID 36699376, 2022). "However, the mechanisms of MECOM and PRDM16 in prognosis and tumor immune infiltration in lung adenocarcinoma (LUAD) remain uncertain." (PMID 35174083, 2022).
melanoma (3 papers, 2015 to 2025). A malignant, usually aggressive tumor composed of atypical, neoplastic melanocytes. "MECOM (3q26), for instance, was among the most frequently mutated genes (3.1 %, 23 of 740 mutations; 36.8 %, 14 of 38 patient samples) within our cohort of patient melanoma samples and was higher than estimated by existing datasets." (PMID 26221190, 2015). "Over 90% of patients with melanoma are carriers of at least one mutation in an epigenetic regulator, especially MLL2 (100%) and MECOM (82.6%)." (PMID 26703582, 2015). "In keeping with our data, MECOM, MLL2 (KMT2D), MLL (KMT2A), ARID2, and CUX1 were among the most frequently mutated epigenetic genes in the TCGA and Broad Institute melanoma cohorts." (PMID 26221190, 2015). "In addition, we have identified that MECOM, a novel, central epigenetic regulatory gene, and TET2/IDH1, critical regulators of DNA demethylation, are frequently mutated in patient melanoma samples." (PMID 26221190, 2015). "Taken together, we hypothesize that MECOM/EVI1 regulates the epigenetic machinery enabling stem cell-like properties in specific melanoma subpopulations." (PMID 26221190, 2015).
ovarian tumor (3 papers, 2009 to 2025). "We demonstrate that MECOM promotes proliferation and migration of MECOM-amplified ovarian tumor cells by regulating KRAS/pERK1/2/ ZEB1 signaling cascade." (PMID 40664642, 2025). "Further, qRT-PCR analysis confirmed that JIB-04 treatment and MECOM siRNA-mediated silencing reduced SUB1 transcript levels in ovarian tumor cells." (PMID 40664642, 2025). "We demonstrate that both PAX8 and MECOM are critical TFs to sustain in vivo growth of ovarian tumors, likely by MECOM acting as a PAX8 cofactor mediating a subset of PAX8 oncogenic functions." (PMID 33903593, 2021). "Importantly PAX8 and MECOM are necessary for ovarian tumor growth in vivo and their signature distinguishes a subset of patients with poor prognosis." (PMID 33903593, 2021).